MMP2 (matrix metallopeptidase 2)
Diseases named in the same sentence as MMP2 in open-access papers (continued):
Sharing a sentence is not in itself a finding about the gene and the disease.
atherosclerosis (continued). "Previous studies have shown that high doses of crocin proportionally reduce the levels of macrophages and their inflammatory derivatives in atherosclerosis, including MCP-1, TNF-α, IL-6, MMP-2, MMP-3, and MMP-9." (PMID 38830933, 2024). "The downregulation of the CD40–CD40L-signaling pathway inactivates matrix metalloproteinase 2 (MMP-2) and MMP-9 in human umbilical vein endothelial cells (HUVECs) and reduces inflammatory responses in atherosclerosis." (PMID 36724021, 2023). "Since MMP-2 plays a vital part in the progression of atherosclerotic plaque, this review sought to systematically investigate the role of MMP-2 in atherosclerosis development in CAD patients." (PMID 37457745, 2023). "MMP2 and MMP9 are a kind of proteases that have been reported to mediate plaque rupture and inflammation in atherosclerosis." (PMID 35783840, 2022). "Significantly, we found that, in a state resembling low-grade inflammation (such as established atherosclerosis), E2 further increased the TNF-α-induced MMP-2 activation in HAECs, with the greatest effect at the lowest concentration." (PMID 36142876, 2022). "In particular, resveratrol increases TIMP-2 and decreases MMP-2 and thereby regulates the MMP-2/TIMP-2 ratio, leading to an improvement of atherosclerosis-induced myocardial fibrosis." (PMID 36615832, 2022). "The down-regulation of MMP2 secretion by UA induced the inhibition of MAPK/ERK signaling pathway, hence inhibiting cell proliferation and atherosclerosis." (PMID 35887090, 2022). "Inhibition of FXa/FIIa can downregulate the activation of the Smad2/3 signaling pathway and MMP2 expression mediated by protease-activated receptor 2 (PAR2) to limit the severity of aortic aneurysm and atherosclerosis." (PMID 35637715, 2022). "Two of these—Gelatinase A and Gelatinase B, (also known as MMP-2 and MMP-9, respectively)—are directly involved in the pathogenesis of coronary thrombosis, atherosclerosis, myocardial infarction, and heart failure." (PMID 33477388, 2021). "Regarding LINC00657 (NORAD), our results are in line with a study which found that LINC00657, which is expressed in vascular endothelial cells, induced angiogenesis during atherosclerosis through the upregulation of VEGF, MMP-2, and MMP-9." (PMID 35237654, 2021). "It is well-known that inflammatory and cardiovascular cell-derived MMP2/9 and have critical roles in VSMC migration and proliferation in development of atherosclerosis." (PMID 33424012, 2020). "Ectopic calcification conceivably leads to fewer MMP-2- and MMP-3-producing cells as in atherosclerosis, whereby calcification often corresponds to areas containing either no cells or dead cells." (PMID 33120982, 2020). "According to the previous studies, IL-37 indeed affects MMP2 and MMP9 expressions in endometriosis, atherosclerosis, and human lung adenocarcinoma." (PMID 32733162, 2020). "In vascular inflammation, such as atherosclerosis, NF-κB upregulates the expression of adhesion molecules (ICAM-1and VCAM-1) and matrix-metalloproteases (MMP-2, and MMP-9), further exacerbating vascular inflammation." (PMID 31717401, 2019). "Therefore, the inhibition of MMP2/9 could be beneficial in the treatment of atherosclerosis." (PMID 30200674, 2018). "Recent knock-out study also suggests that MMP2 and MMP9 are crucial in development of arterial lesions resulting in atherosclerosis." (PMID 30046331, 2018). "MMP-2 and TIMP-2 expression can be regulated by fluid shear stress, which are important factors contribute to atherosclerosis." (PMID 29435135, 2018). "Our results verified that TNF-α administration substantially increased the levels of inflammatory cytokines, such as interleukins, MCP-1, MMP-2, and MMP-9, that mainly contribute to the development of vessel dysfunction in atherosclerosis." (PMID 30577658, 2018). "The zinc-containing endopeptidases, MMP-2/-9, are involved in the breakdown of ECM occurred in amyloidosis, aging, hypertension and atherosclerosis." (PMID 29085385, 2017).
atherosclerosis (continued). "Significantly higher serum concentrations of MMP-2 and MMP-9 are found in patients with T2D and atherosclerosis." (PMID 27490532, 2016). "For atherosclerosis event, MMP-9 and MMP-2 play key role by degrading ECM and facilitating VSMC migration from media to intima of blood vessel." (PMID 27066292, 2016). "Evidence shows that matrix metalloproteinase (MMP)-2 and MMP-9 are related to the pathogenesis of atherosclerosis." (PMID 26690114, 2015). "The expressions of MMP-2 and MMP-9 in atherosclerosis are regulated via various pathways, such as p38 mitogen activated protein kinase (MAPK), extracellular signal regulated kinase 1 and 2 (ERK1/2), Akt, and nuclear factor kappa (NF-κB)." (PMID 26690114, 2015). "Apart from MMP-2, the role of MMP-9 in the pathogenesis of vascular changes in atherosclerosis has also been established." (PMID 25145866, 2014). "The main inflammatory cytokines participating in atherosclerosis, IL-1β, TNF-α, MCP-1 and MMP-2, were detected in the plaque." (PMID 24755612, 2014). "Matrix metalloproteinase 2 (MMP2) plays critical roles in various diseases, such as atherosclerosis and cancer, and has been suggested to contribute to the instability of atherosclerotic plaque." (PMID 24589243, 2014). "In animal models of atherosclerosis, myeloid cell‐specific overexpression of lncAPAT enhanced the atherosclerotic plaque lesion area, increased the ratio of type III/type I collagen, and promoted the expression of MMP9 and MMP2 in aortic plaques." (PMID 41527512, 2026). "Increased MMP2 in the intima has also been observed in the thickened intima of older monkeys as compared to the thin intima of the young, both without atherosclerosis." (PMID 40076574, 2025). "We found an overall reduced expression of ET receptors and smooth muscle actin (SMA), a marker of healthy vascular smooth muscle cells, in atherosclerotic plaques, whereas the levels of ET-1 and matrix metalloproteinase 2 (MMP-2), a marker of atherosclerosis progression, remained unchanged." (PMID 40076930, 2025). "It has been reported that renal denervation increases MMP-2 in both animals and humans, and an increase in MMP-2 may adversely affect the stability of severe atherosclerosis." (PMID 37685939, 2023). "Studies revealed that Piezo1 promotes atherosclerosis formation by regulating the NF-κB pathway in vascular endothelial cells and can activate membrane-type matrix metalloproteinase(MMP)-1 and MMP-2 to promote angiogenesis, thereby promoting unstable plaque formation." (PMID 35751027, 2022). "An experimental study used smooth muscle cells from rat thoracic aorta (A7r5 cell line) to analyze the influence of different exposure times (up to 48 h) and concentrations of DEHP (2, 3.5, 7, 10.5, 14, 17.5 ppm) on matrix metalloproteinase (MMP)-2 and MMP-9, that are related with atherosclerosis." (PMID 32707888, 2020). "Inhibition of MMP-2 and MMP-9 has been employed as a potential strategy to prevent atherosclerosis." (PMID 32908568, 2020). "To determine whether liquefaction of the brain following stroke shares other characteristics with atherosclerosis we measured the levels of OPN, IL-18, MMP-2, MMP-3, and MMP-8." (PMID 30417081, 2018). "The reduction of MMP-2 and -9, and TNF-α by mesoglycan could have a positive role in contrasting atherosclerosis progression." (PMID 28272312, 2017). "Significantly increased levels of MMP-2, MMP-2/TIMP-2 ratio and lower TIMP-1 suggests that these factors may be involved in the pathogenesis of atherosclerosis in CKD patients." (PMID 26843213, 2016). "In this study, significantly increased levels of MMP-2, MMP-2/TIMP-2 ratio and lower levels of TIMP-1 were observed, suggesting that these factors may be involved in the pathogenesis of atherosclerosis in patients with CKD." (PMID 26843213, 2016).
atherosclerosis (continued). "Accumulating clinical and experimental evidence have shown that MMP-2 and MMP-9 content and activity are correlated with atherosclerosis development, since they could decrease basement membrane and promote SMCs migration and proliferation." (PMID 25661015, 2015). "Furthermore, the expression of MMP-2 and MMP-9 in monocytes is particularly important in penetrating the first basement membrane barrier of the ECM in the development of atherosclerosis." (PMID 25574228, 2015). "MMP-2 is constitutively expressed in VSMCs in normal arteries, and MMP-2 expression and activity levels may contribute to the pathogenesis of atherosclerosis by facilitating the migration of VSMCs." (PMID 24926361, 2014). "Among this family of related proteases, MMP-1 (also called interstitial collagenase), MMP-2 (gelatinase-A), and MMP-9 (gelatinase-B) have been consistently described as significant contributors in several cardiovascular diseases including atherosclerosis, hypertension, CAD, and ACS." (PMID 23951304, 2013). "UA showed an efficient activity against in vitro leptin-induced atherosclerosis in rat vascular smooth muscle cells; in terms of molecular mechanism, UA exhibited an inhibitory effect on ERK1/2 activation, NF-kB expression, and leptin-induced MMP2 activity, hence decreasing ROS production." (PMID 35887090, 2022). "Significantly, in a low-grade inflammation state, such as established atherosclerosis, E2 promotes the destabilization of the atherosclerotic plaque by inducing the expression of molecules such as MCP-1 and MMP-9 and by increasing the activity of MMP-2 in the endothelial cells." (PMID 36142876, 2022). "Thus, factors that regulate the expression of MMP-2 and MMP-9 in monocytes may affect the process of atherosclerosis development." (PMID 25574228, 2015).
diabetes (129 papers, 2007 to 2026). "Elevated baseline levels of MMP-9 and MMP-2 are suggested to be associated with vascular complications in diabetes." (PMID 39685536, 2024). "Understanding the cellular pathways involving MMP-2 in the context of diabetes can provide insights into the mechanisms underlying diabetic complications and potential therapeutic targets for intervention." (PMID 39769454, 2024). "Analyses of associations with hyperlipidemia, between TIMP-2 and diabetes, as well as the association between MMP-2 isoforms and TIMP-2 with hypertension were also impossible in our control group–also due to the tiny tissue samples." (PMID 30794673, 2019). "Duration of diabetes appeared to be the major confounder in the association between MMP-2 and cfPWV and was significantly correlated with age." (PMID 29070037, 2017). "MMP‐2 concentrations in urine correlated with clinical parameters associated with increased risk for diabetic nephropathy (eg elevation in glycated HbA1c, prolonged duration of diabetes, renal hyperfiltration and microalbuminuria)." (PMID 33855203, 2021). "This exercise-induced increase in MMP2 levels was speculated to be a protective mechanism against obesity and associated diseases such as type 2 diabetes mellitus." (PMID 31590286, 2019). "However, we cannot exclude that both age and duration of diabetes were the major confounders in the association between MMP-2 and cfPWV." (PMID 29070037, 2017). "Similarly, elevated MMP2 has been implicated in the development of diabetes mellitus, and a MMP inhibitor, PD166793, reduces blood glucose in Zucker diabetic rats." (PMID 25333278, 2014). "Our results suggest that rosiglitazone may play an atheroprotective role via its beneficial effects on gelatinases (MMP-2 and −9) throughout inflammatory process particularly in the high cardiovascular risk population of patients with diabetes mellitus." (PMID 22716287, 2012). "Evidence supports the theory that hyperglycaemia associated with diabetes causes dysregulation of MMPs in primary cells from the vasculature (macrophages and endothelial cells), and that both MMP‐2 and MMP‐9 may be involved in the rupture of atherosclerotic plaques." (PMID 33855203, 2021). "A study investigated the function of MMP2 in the progression of proteinuria and renal damage following the induction of hypertension or diabetes in MMP2 knockout rats." (PMID 40492135, 2025). "Our study found that elevated MMP-2 levels (>1519.3 ng/mL) correlated with older age, higher diabetes prevalence, lower HDL levels, increased NT-proBNP and hs-TnT levels, and more severe systolic dysfunction." (PMID 39334904, 2024). "In diabetes, elevated MMP-2 activity exacerbates complications such as nephropathy, retinopathy, and cardiovascular disease." (PMID 39769454, 2024). "Simple logistic regression analyses showed that HIV seropositivity, diabetes mellitus, older age, CVD risk, and Factors 2 (sTNFRII and VCAM-1) and 4 (MMP-2) were significantly associated with DSP (ps < 0.05)." (PMID 38673830, 2024). "For MMP-2 levels (≤1519.3 ng/mL and >1519.3 ng/mL), significant differences were observed in age, diabetes prevalence, HDL levels, NT-proBNP, hs-TNT, dyspnea severity, and 6MWT results, indicating distinct disease trajectories and risk profiles." (PMID 39334904, 2024). "Further research is needed to elucidate the specific roles of MMP-2 in diabetes-related pathologies and to explore its potential as a target for therapeutic strategies." (PMID 39769454, 2024). "Patients with MMP-2 levels exceeding 1519.3 ng/mL were generally older (57.5 years vs. 53.5 years, p = 0.04) and had a higher prevalence of diabetes (23.4% vs. 9.7%, p = 0.04)." (PMID 39334904, 2024). "Concentrations of serum MMP-2 and OPN are increased in patients with obesity and type 2 diabetes mellitus (T2D), while OPN has been implicated in mediating the relationship between inflammation, obesity and diabetes." (PMID 36648516, 2023).
diabetes (continued). "In the study concerning MMP-2, an additional criterion for the selection of the subjects was used; other types of diabetes, autoimmune diseases and a positive anti-GAD, anti-IA2 or ICA autoantibody response were assumed as excluding factors." (PMID 36142480, 2022). "In the present study, diabetes upregulated MMP2, TIMP1, and TIMP2 mRNA expression in the human rotator cuff." (PMID 35453426, 2022). "The temporal and spatial locations of both MMP-2 isoforms were examined in a mouse model of type 1 diabetes mellitus induced by streptozotocin and in the db/db mouse model of type 2 diabetes mellitus." (PMID 33732288, 2021). "Patients with diabetes, as a whole group, demonstrated increased serum levels of L-citrulline (p = 0.006), MMP-2 (p = 0.0002), and MMP-3 (p = 0.008) as compared to controls." (PMID 35011813, 2021). "In obese diabetic ZDF rats, there were increased protein levels of 63 kDa MMP-2 and treatment with quercetin prevented the diabetes-induced changes." (PMID 33923282, 2021). "The findings of the current study also demonstrate that diabetes development involves changes in MMP-2 and MMP-28 and attenuation of antioxidant defense by SOD." (PMID 33923282, 2021). "Rodent models of diabetes reveal decreased expression and/or proteolytic activity of MMP-2 in renal tissues, suggesting decreased degradation of CIV in the GBM." (PMID 34069322, 2021). "The molecular mechanisms in the pathways regulating TIMP-2 and MMP-2 expressions have been introduced in many diseases, especially diabetes, or different diseases other than diabetes." (PMID 33777140, 2021). "The recent results advocate that due to diabetes, the overexpression of MMP-2 and MMP-9 in the retina inhibits cell proliferation and differentiation and accelerates apoptosis, a phenomenon that precedes the development of histopathology characteristic of DR." (PMID 32403389, 2020). "Therapeutic treatment with MMPI blocked diabetes-induced increase in plasma MMP2 and -9 activities by 2- and 1.2-fold, respectively, confirming that this inhibitor reduces the activity of both MMPs in vivo." (PMID 32037077, 2020). "In patients with diabetes different MMPs such as MMP-2 and MMP-9 are increased in urine, especially in patients with albuminuria and established renal injury." (PMID 32046355, 2020). "In the late period of diabetes, decreased activity of MMP-2 and MMP-9 is observed with increased activity of tissue inhibitor of metalloproteinases-1 (TIMP-1)." (PMID 32403389, 2020). "Generally, either cancer itself, diabetes, or both induced abnormal MMP-2 and MMP-9 overproduction, which should be further studied to address these unanswered questions." (PMID 33251135, 2020). "Other associations found in this study, such as MMP-10 with age and diabetes and MMP-2 with age, hypertension and 90-days mortality, were only significant in VdH possibly explained by larger sample size and statistical power of this cohort." (PMID 32587306, 2020). "Blockade of MMP2 and -9 attenuated diabetes-induced changes in glomerular endothelial glycocalyx Sdc4 and glomerular SDC4 at the mRNA and protein levels, suggesting a reduction in glomerular endothelial SDC4 shedding." (PMID 32037077, 2020). "MMP2 was significantly increased in patients with diabetes and in women with metabolic syndrome, which was consistent with our findings." (PMID 32455133, 2020). "Treatment with MMP-2/9 inhibitor I for 21 days, started six weeks after diabetes induction, restored endothelial glycocalyx depth and coverage and attenuated diabetes-induced albuminuria and reduced glomerular albumin permeability." (PMID 32037077, 2020). "According to these studies, diabetes duration has a significant role on the alteration of urinary MMP2 and MMP9." (PMID 30396876, 2019). "We examined the serum MMP-2 and MMP-9 activity at 72 h after MCAO and found that the development of diabetes increased the serum levels of MMP-2 and MMP-9, which were further elevated after rt-PA treatment." (PMID 30953513, 2019).